SAMD9 (sterile alpha motif domain containing 9)
Description:
Double-stranded nucleic acid binding that acts as an antiviral factor by playing an essential role in the formation of cytoplasmic antiviral granules. May play a role in the inflammatory response to tissue injury and the control of extra-osseous calcification, acting as a downstream target of TNF signaling. Involved in the regulation of EGR1, in coordination with RGL2. May be involved in endosome fusion.
Synonyms: C7orf5; DRIF1; KIAA2004; OEF1; FLJ20073; M7MLS2; MIRAGE; NFTC; OEF2
Tractability: PROTAC: ubiquitination databases record sites on it; its protein half-life has been measured.
Gene: Protein-coding gene on chromosome 7 (93,099,513 to 93,118,023, reverse strand). Ensembl gene ENSG00000205413.
Subcellular location: Cytoplasm
Subcellular location (Human Protein Atlas): Cytosol; Vesicles
Gene Ontology:
Molecular function: protein binding
Biological process: endosomal vesicle fusion
Cellular component: cytoplasm; cytosol
Genetic constraint (gnomAD): Loss-of-function variants: 4 observed, 4.47 expected, observed/expected ratio (o/e) 0.9, 90% interval 0.43 to 1.77. That is too few expected variants to judge how well the gene tolerates losing a copy. Missense variants: 1,597 observed, 1,919.2 expected, observed/expected ratio (o/e) 0.83, 90% interval 0.8 to 0.87. Synonymous variants: 635 observed, 670.6 expected, observed/expected ratio (o/e) 0.95, 90% interval 0.89 to 1.01.
Gene-disease validity (ClinGen):
ClinGen rates the evidence that SAMD9 causes each of these diseases.
normophosphatemic familial tumoral calcinosis (autosomal recessive): Limited.
Homologues: Orthologues: chimpanzee SAMD9 (99% identical), macaque SAMD9 (95% identical), pig SAMD9 (80% identical), guinea pig SAMD9 (77% identical), rat Samd9 (77% identical), rabbit SAMD9 (66% identical), zebrafish SAMD9 (38% identical), tropical clawed frog samd9l (33% identical). Paralogues in human: SAMD9L (60% identical).
Diseases named in the same sentence as SAMD9 in open-access papers:
SAMD9 is named in the same sentence as 80 diseases in open-access papers, as found by Europe PMC text mining. Sharing a sentence is not in itself a finding about the gene and the disease. The quoted sentences say what the papers report.
MIRAGE syndrome (31 papers, 2017 to 2026). An autosomal dominant condition caused by mutation(s) in the SAMD9 gene, encoding sterile alpha motif domain-containing protein 9A. "Herein, we present the case of a 32‐week premature newborn female with clinical features consistent with MIRAGE syndrome associated with a previously unreported de novo mutation, SAMD9 G1048R, which was identified at 23 days of age by whole exome sequencing." (PMID 41268294, 2025). "MIRAGE syndrome is a multi‐organ disease caused by gain‐of‐function (GOF) mutations in the viral restriction factor SAMD9." (PMID 41268294, 2025). "MIRAGE syndrome, stemming from pathogenic SAMD9 variants, manifests as a congenital multisystem disorder with features like 46, XY differences in sex development (DSD), small for gestational age (SGA), and adrenal insufficiency (AI)." (PMID 38539345, 2024). "Another paper presented two patients with MIRAGE syndrome that exhibited activating SAMD9 mutations along with second-site reversion nonsense mutations on the same allele." (PMID 38539345, 2024). "SAMD9 pathogenic variants are commonly associated with MIRAGE syndrome, which consists of five out of the six of the following clinical features: myelodysplasia, infection, growth restriction, adrenal hypoplasia, genital phenotypes, and enteropathy." (PMID 37160314, 2023). "Other SAMD9 pathogenic variants have been associated with MIRAGE syndrome, bone marrow failure, a predisposition to monosomy 7 MDS, and AML." (PMID 37160314, 2023). "The missense gain-of-function variants causing MIRAGE syndrome result in decreased cell proliferation and growth restriction in in vitro model systems, highlighting the innate role of SAMD9 as a growth repressor." (PMID 36060959, 2022). "Mutations in SAMD9 have been described in patients with MIRAGE syndrome, a severe multisystem disorder." (PMID 36357925, 2022). "Heterozygous de novo variants in SAMD9 cause MIRAGE syndrome, a complex multisystem disorder involving Myelodysplasia, Infection, Restriction of growth, Adrenal hypoplasia, Genital phenotypes, and Enteropathy." (PMID 36060959, 2022). "This study describes the case of a patient who presented with FD-like symptoms and myelodysplastic syndrome (MDS) with monosomy 7 and was posthumously diagnosed as having MIRAGE syndrome due to a rare SAMD9 variant." (PMID 34253717, 2021). "MIRAGE syndrome results from heterozygous gain-of-function missense mutations in the growth repressor, sterile alpha domain containing 9 (SAMD9)." (PMID 33381483, 2020). "The syndromic category includes four different forms which are AAA syndrome (AAAS mutations), IMAGE syndrome (CDKN1C mutations), MIRAGE syndrome (SAMD9 mutations), and a syndrome with MCM4 mutations." (PMID 31208161, 2020). "We report a patient with MIRAGE syndrome who possesses a de novo novel missense variant in the SAMD9 gene." (PMID 32194975, 2020). "We present here a case of MIRAGE syndrome due to a heterozygous missense variant (c.2920G>A; p.E974K) mutation in the SAMD9 gene." (PMID 31208161, 2020). "We herein present a case of MIRAGE syndrome with a novel de novo missense variant [NM_017654.4:c.4435 G > T, p.(Ala1479Ser)] in the SAMD9 gene." (PMID 32194975, 2020). "Accordingly, we identified a likely pathogenic de novo variant in the SAMD9 gene of a patient with MIRAGE syndrome." (PMID 32194975, 2020). "In summary, we described the clinical characteristics of a patient with MIRAGE syndrome possessing a novel variant in the SAMD9 gene." (PMID 32194975, 2020). "MIRAGE syndrome is caused by a gain-of-function variant in the SAMD9 gene on the long arm of chromosome 7 (7q21.2), encoding sterile alpha motif domain-containing protein 9, which functions in endosome fusion and regulates cell growth in in vitro models." (PMID 32194975, 2020). "Here we present a case of MIRAGE syndrome due to a heterozygous missense variant (c.2920G>A; p.E974K) mutation in the sterile alpha motif domain-containing protein-9 (SAMD9) gene." (PMID 31208161, 2020).
MIRAGE syndrome (continued). "We herein report a Japanese patient with MIRAGE syndrome carrying a novel de novo heterozygous missense variant in the SAMD9 gene (c.4435 G > T; p.Ala1479Ser)." (PMID 32194975, 2020). "De novo as well as familial germ-line mutations in the SAMD9 gene have been discovered to cause the MIRAGE syndrome." (PMID 29535429, 2018). "The pathogenesis of SGA and DSD in MIRAGE syndrome seems multifactorial, including intrinsic growth restriction and placental insufficiency both related to pathogenic SAMD9 variants." (PMID 30403727, 2018). "The first two studies of MIRAGE syndrome were reported by endocrinology research laboratories of Japan and United Kingdom, and as many as 94% of the SAMD9 variant-carrying patients had adrenal insufficiency (AI) in these studies." (PMID 30403727, 2018). "Assessment of cell growth with use of time-lapse microcopy revealed potent growth-restricting capacity of Phe1017Val-SAMD9, which is a common characteristic of MIRAGE syndrome-associated SAMD9 variants." (PMID 30403727, 2018). "It is also noteworthy that 46,XY DSD and SGA are simultaneously observed in several rare genetic defects, including IMAGe syndrome due to CDKN1C variants and MIRAGE syndrome due to SAMD9 variants." (PMID 30403727, 2018). "MIRAGE syndrome, a congenital multisystem disorder due to pathogenic SAMD9 variants, describes a constellation of clinical features including 46,XY disorders of sex development (DSD), small for gestational age (SGA) and adrenal insufficiency (AI)." (PMID 30403727, 2018). "Recent work has identified mutations in SAMD9 in children with myelodysplasia, infection, restriction of growth, adrenal hypoplasia, genital phenotypes, and enteropathy, named MIRAGE syndrome (OMIM #617053)." (PMID 29535429, 2018). "A de novo SAMD9 variant G1048R is associated with MIRAGE syndrome symptoms in a neonate." (PMID 41268294, 2025). "MIRAGE syndrome is a recently described congenital condition characterized genetically by heterozygous gain-of-function missense mutations in the growth repressor sterile alpha domain containing 9 (SAMD9) located on the arm of chromosome 7 (7q21.2)." (PMID 38539345, 2024). "The patient was diagnosed with MIRAGE syndrome with SAMD9 gene mutation." (PMID 37745698, 2023). "This new SAMD9 variant (p.F437S) also causes MIRAGE syndrome." (PMID 34253717, 2021). "Finally, the spectrum of clinical disorders associated with SAMD9/9L mutations, including MIRAGE syndrome and various bone marrow failure syndromes, underscores the importance of elucidating how domain organization and specific residues modulate SAMD9/9L function." (PMID 40291743, 2025). "At least 56 patients have been reported to develop either MIRAGE syndrome associated with SAMD9 mutations, with a median age of diagnosis at 1.18 years, thus this case represents an early identification of a SAMD9 mutation associated with signs and symptoms of MIRAGE syndrome." (PMID 41268294, 2025). "MIRAGE syndrome is a recently discovered rare genetic disease characterized by myelodysplasia (M), infection (I), growth restriction (R), adrenal hypoplasia (A), genital phenotypes (G), and enteropathy (E), caused by a gain-of-function mutation in the SAMD9 gene." (PMID 32787808, 2020). "In addition to the effects of variant site on the clinical course of MIRAGE syndrome, there is evidence of the clinical impact of additional genetic signatures in MIRAGE syndrome, which includes the loss of chromosome 7 on which the SAMD9 gene variant responsible for MIRAGE syndrome is present." (PMID 32194975, 2020). "MIRAGE syndrome is a recently discovered rare genetic disease characterized by myelodysplasia (M), infection (I), growth restriction (R), adrenal hypoplasia (A), genital phenotypes (G), and enteropathy (E), caused by a gain-of-function mutation in the SAMD9 gene on the arm of chromosome 7 (7q21.2)." (PMID 32787808, 2020).
MIRAGE syndrome (continued). "Consistently, SAMD9 GOF MIRAGE syndrome patients frequently show evidence of primary immune defects including NK cell lymphopenia and neutropenia and are prone to recurrent invasive infections." (PMID 41268294, 2025). "The expression of the profile of SAMD9 corresponds to the clinical spectrum of organ‐specific disease manifestations in MIRAGE syndrome." (PMID 41268294, 2025). "The authors showed that complex dynamic somatic changes in SAMD9 and the SAMD9/SAMD9L locus on chromosome 7q are associated with the distinct MIRAGE syndrome phenotype and modify survival in affected patients." (PMID 38539345, 2024). "Loss of chromosome 7 and UPD of 7q have previously been described in patients with MIRAGE syndrome (MIM #617053), this is believed to be an adaptation to the growth-suppressing effect of the SAMD9 variants." (PMID 39346101, 2023). "Since the first description of MIRAGE syndrome in 2016, there has been an increasing number of publications reporting patients with MIRAGE features with variants in SAMD9, and the phenotypic spectrum of SAMD9-related conditions has now expanded." (PMID 36060959, 2022). "Analysis of RNA expression in several adult and fetal human tissues shows high levels of SAMD9 in the esophagus, fetal adrenal, colon, bone marrow, thymus, lung and fetal testis, which are tissues particularly affected in MIRAGE syndrome." (PMID 36060959, 2022). "Germline mutations in the SAMD9 and SAMD9L gene, located on chromosome 7, are associated with a clinical spectrum of disorders including the MIRAGE syndrome, ataxia–pancytopenia syndrome and monosomy 7 myelodysplastic syndrome." (PMID 35572556, 2022). "Similar mutations in SAMD9 and SAMD9L have previously been observed in disorders associated with BM abnormalities, such as MIRAGE syndrome and Ataxia-Pancytopenia syndrome (ATXPC), respectively." (PMID 33731850, 2021). "MIRAGE syndrome, another known cause of syndromic PAI, is due to a heterozygous SAMD9 gain of function mutations and is characterized by myelodysplasia, infection, restriction of growth, adrenal hypoplasia, genital anomalies and enteropathy." (PMID 32938577, 2021). "This article is dedicated to the late Dr. Paolo Ghirri, whose collaborations helped us to understand the role of SAMD9 in MIRAGE syndrome." (PMID 33381483, 2020). "Mutations in the Sterile alpha motif domain containing 9 (SAMD9) gene have been described in patients with severe multisystem disorder, MIRAGE syndrome, but also in patients with bone marrow (BM) failure in the absence of other systemic symptoms." (PMID 31620126, 2019). "An independent study has very recently reported a similar, though distinct, phenotype caused by SAMD9 mutations, characterized by IUGR, infections, enteropathy, adrenal hypoplasia, and underdeveloped external genitalia (MIRAGE syndrome)." (PMID 28346228, 2017). "In conjunction with IBMF, MIRAGE syndrome patients show an increased risk of myelodysplastic syndrome (MDS) associated with microdeletions in chromosome 7 (monosomy 7), indeed 17% of pediatric patients with MDS have mutations in SAMD9 and its paralogue SAMD9L." (PMID 41268294, 2025). "This case report describes the finding of a germline SAMD9 variant (c.4460A > G) in a patient with a new diagnosis of MDS with excess blasts without underlying MIRAGE syndrome." (PMID 37160314, 2023). "It would be of interest to study cellular ultrastructure from individuals with other gain-of-function or loss-of function changes in SAMD9, who do not have classic MIRAGE syndrome features, to see if similar changes are seen there too." (PMID 38434662, 2023). "In addition to the well-described gonadal defects that can affect both the testis and ovary, a range of additional endocrine features have been reported with MIRAGE syndrome and SAMD9 disruption." (PMID 36060959, 2022). "Furthermore, FGR is a key feature of specific conditions such as MIRAGE syndrome (SAMD9) and IMAGe syndrome (CDKN1C)." (PMID 36419940, 2022).
MIRAGE syndrome (continued). "This patient did not have features typical for MIRAGE syndrome, which was initially ascribed to SAMD9 mutations." (PMID 32555368, 2020). "The conclusion is therefore that SAMD9 mutations underlying the MIRAGE syndrome are GOF and the negative effect on cellular growth puts a selection pressure on the cells to lose their mutated copy." (PMID 29535429, 2018). "Germline mutations in the SAMD9 and SAMD9L genes, located in tandem on chromosome 7, are associated with a clinical spectrum of disorders including the MIRAGE syndrome, ataxia–pancytopenia syndrome and myelodysplasia and leukemia syndrome with monosomy 7 syndrome." (PMID 29535429, 2018). "MIRAGE syndrome is usually diagnosed in a child with suggestive features when genetic testing, whole exome sequencing (WES), reveals a heterozygous gain-of-function missense mutations in the growth repressor sterile alpha domain containing 9 (SAMD9) located on the arm of chromosome 7 (7q21.2)." (PMID 38539345, 2024). "SAMD9 genetic testing for patients with MDS could help identify family members who would require routine screening for the various clinical presentations of either MIRAGE syndrome or MDS, as well as consideration of fertility preservation of that patient." (PMID 37160314, 2023). "Taken together, the higher placental expression of SAMD9 in later pregnancy coupled with evidence of abnormal placental development in affected patients, could be contributing factors to poor growth and fetal distress seen in MIRAGE syndrome, and a reason these babies are delivered early." (PMID 36060959, 2022). "Consistent with the presentation of MIRAGE syndrome with IBMF, SAMD9 activation in both human and murine models leads to deleterious effects, particularly on hematopoietic stem cells, including impaired cellular proliferation, accrual of DNA damage, and apoptosis." (PMID 41268294, 2025). "In conclusion, we conducted the first genetic screen of SAMD9 variants in a patient cohort of 46,XY DSD SGA without AI, and showed that MIRAGE syndrome is a rare cause of the condition." (PMID 30403727, 2018). "SAMD9 is highly expressed in fetal adrenal organs and MIRAGE syndrome presents with primary adrenal insufficiency in roughly 78.8% of patients, although “non‐adrenal” MIRAGE syndrome patients are not infrequent and occur in 21.2% of patients." (PMID 41268294, 2025).
myelodysplastic syndrome (17 papers, 2013 to 2025). A clonal hematopoietic disorder characterized by dysplasia and ineffective hematopoiesis in one or more of the hematopoietic cell lines. "Humans with deleterious mutations in SAMD9 present disease that ranges from lethality at a young age to a predisposition to myelodysplastic syndromes (MDS) that often require bone marrow transplantation." (PMID 36103568, 2022). "However, a few rare loss-of-function variants in SAMD9 have also been identified in myelodysplastic syndrome patients." (PMID 35739278, 2022). "However, when monosomy 7 occurs there is a risk of myelodysplastic syndrome due to loss of SAMD9, SAMD9L, GATA2 and other factors, and an additional risk of leukemia if further somatic changes occur." (PMID 36060959, 2022). "Deleterious mutations of SAMD9 are key enabling factors for some autoimmune diseases and cancers, as well as the pathogenesis of myelodysplastic syndromes (MDS), esophageal and lung tumorigenesis." (PMID 33936093, 2021). "In the pediatric age group, germline abnormalities in GATA2, SAMD9, and SAMD9L are the most common causes of myelodysplastic neoplasms and AML." (PMID 39062641, 2024). "In addition to the classical cBMF, several germline defects predisposing individuals to MF and potentially evolving to myelodysplastic syndrome (MDS) and leukemia have been increasingly discovered (GATA2, SAMD9, and DADA2) in the last few years." (PMID 38396760, 2024). "Very recently, a total of ten SAMD9 variant carriers with seemingly no adrenal problems were discovered among pediatric patients with bone marrow failure or myelodysplastic syndrome." (PMID 30403727, 2018). "Germline mutations in sterile alpha motif domain protein 9 (SAMD9) and its paralogue SAMD9-like (SAMD9L), which are located in tandem on chromosome 7q21, are associated with human syndrome with a propensity for bone marrow failure and myelodysplastic syndrome (MDS) with monosomy 7 and 7q deletion." (PMID 34868061, 2021). "Similarly, loss of SAMD9 and SAMD9L by monosomy 7 or monosomy 7q (–7/7q–) is well established in myeloid lineage malignancies, and disruption of SAMD9L has been shown to be associated with the development of myelodysplastic syndrome (MDS) in mice and humans." (PMID 28346228, 2017). "Lastly, the human SAMD9 and SAMD9L genes were both classified as myeloid tumor suppressors, as they are localized within a microdeletion cluster associated with myeloid disorders, such as juvenile myelomonocytic leukemia (JMML), acute myeloid leukemia (AML), and myelodysplastic syndrome (MDS)." (PMID 23758988, 2013).